ENSG00000285526 (novel protein)
Gene: Protein-coding gene on chromosome 19 (35,106,510 to 35,124,297, forward strand). Ensembl gene ENSG00000285526.
Genetic constraint (gnomAD): Loss-of-function variants: 15 observed, 20.14 expected, observed/expected ratio (o/e) 0.74, 90% interval 0.5 to 1.15. Missense variants: 141 observed, 149.93 expected, observed/expected ratio (o/e) 0.94, 90% interval 0.82 to 1.08. Synonymous variants: 68 observed, 56.88 expected, observed/expected ratio (o/e) 1.2, 90% interval 0.98 to 1.46.